PTPRO (protein tyrosine phosphatase receptor type O)
Diseases named in the same sentence as PTPRO in open-access papers (continued):
Sharing a sentence is not in itself a finding about the gene and the disease.
tumor (continued). "In addition, the expression of PTPRO exhibited strong relevance with tumor-infiltrating immune cells, which suggested the potential role of PTPRO in anti-tumor immunity." (PMID 35003364, 2021). "We noticed however, that a few CT-RERG-negative tumor samples nevertheless displayed DNA hypermethylation of PTPRO and RERG, thereby suggesting that transcriptional overlap may not be the only mechanism directing epigenetic silencing onto these promoters." (PMID 34462486, 2021). "PTPRO plays a critical role in regulating cancer inflammation and tumor immunity." (PMID 31827380, 2019). "Multiple signaling pathways are involved in the tumor suppressor function of PTPRO in HCC." (PMID 29558404, 2018). "Although PTPRO methylation was weakly associated with ER- and PR- status, these factors had no prognostic value in the current tumor series (data not shown)." (PMID 24919593, 2014). "In addition, the protein tyrosine phosphatase receptor type O (PTPRO) is a tumor suppressor." (PMID 38835784, 2024). "In addition, due to the CRCI research using tumor-bearing animals to mimic humans with newly diagnosed cancer is necessary to screen potential drug candidates against CRCI, we investigated the potential relevance of PTPRO to cognitive function in tumor-bearing mice." (PMID 37485875, 2023). "Furthermore, the GESA result also revealed the potential role of PTPRO in tumor immunology." (PMID 35003364, 2021). "Apart from the regulatory role of PTPROt in T cell activation, proliferation and differentiation, a recent study reported the governance of PTPRO on T cell quantity in a novel indirect way through downregulating the expression of PD-L1 on the surface of tumor-associated macrophages (TAMs)." (PMID 34880876, 2021). "Expression of PTPRO was negatively correlated with p-JAK2, p-STAT3, Bcl-2, and Snail levels in LUAD tumor samples." (PMID 38182570, 2024). "In CRC, the protein tyrosine phosphatase receptor type O gene (PTPRO) promotes the expression of FAO enzymes by upregulating PPAR-α, thereby promoting tumor metastasis." (PMID 39103344, 2024). "According to public datasets and LUAD specimens, we found that PTPRO is downregulated in LUAD, and its expression is negatively correlated with tumor size and TNM stage." (PMID 38182570, 2024). "To explore the molecular mechanism of the tumor-suppression role of PTPRO in LUAD, we retrieved the PTPRO correlation genes from TCGA database for pathway enrichment analysis." (PMID 38182570, 2024). "Protein tyrosine phosphatase receptor type O (PTPRO), belonging to the R3 subtype family of receptor-type protein phosphatase, has been reported to act as a tumor suppressor through its anti-inflammation and anti-immunity activity." (PMID 36986884, 2023). "HCC growth can also be slowed by ERα-mediated activation of protein tyrosine phosphatase receptor type O (PTPRO), a tumour inhibitor in many malignancies." (PMID 37752418, 2023). "High PTPRO expression was related to high infiltration levels of CD8+ T cells, as well as macrophages, activated dendritic cells (aDCs), tumor-infiltrating lymphocytes (TILs), and Th1 cells." (PMID 36003382, 2022). "Collectively, these results suggest that PTPRO plays an essential role in mediating the reprogramming of TIME, thereby suppressing tumor progression." (PMID 36003382, 2022). "Protein tyrosine phosphatase receptor type O (PTPRO), a member of the PTP family, has been reported that it can function as a tumor suppressor and prognostic factor in various cancers." (PMID 36003382, 2022). "We and others have demonstrated that PTPRO is capable of dephosphorylating RTKs such as ERBB2 and EPH receptors and repressing tumor growth." (PMID 35431974, 2022). "Protein tyrosine phosphatase receptor type O (PTPRO) is one of the receptor types of phosphotyrosine phosphatase (PTP), known to be a tumor suppressor in various cancers." (PMID 35096574, 2021).
tumor (continued). "Protein tyrosine phosphatase receptor-type O (PTPRO) is classified as a receptor-type PTP of the R3 subtype and exhibits characteristics of a tumor suppressor in multiple cancers." (PMID 24919593, 2014). "Protein tyrosine phosphatase receptor-type O (PTPRO), a type III member of the receptor-type PTP family, has come to the front as a tumor suppressor in multiple cancers." (PMID 24090193, 2013). "When tumor were HER2-positive, patients with methylated-PTPRO had a tendency for poor overall survival compared to those of unmethylated-PTPRO, but the differences were not significant (n = 78, HR, 5.112; CI 95%, 0.658-39.723; P = 0.119)." (PMID 24090193, 2013). "Analysis of 90 pairs of clinical LUAD specimens revealed significantly lower PTPRO levels in LUAD compared with adjacent non-tumor tissue, as well as a negative correlation of PTPRO expression with tumor size and TNM stage." (PMID 38182570, 2024). "Receptor-type protein tyrosine phosphatase (PTPRO) has been shown to be a tumor suppressor in a variety of tumor; however, its role in LUAD has never been reported." (PMID 36816740, 2023). "Moreover, the expression of PD-L1 in tumor cells is largely supported by the activation of EGFR, MAPK, PI3K/Akt or Jak/Stat3 pathways, some of which are found to be restrained by PTPRO in several cancer types." (PMID 34880876, 2021). "In addition to a potent tumor suppressor, PTPRO/PTPROt also plays a crucial role in the signaling pathways in B cells, T cells and macrophages." (PMID 34880876, 2021). "Lack of GABRQ/GABRA3 and PTPRO/RERG promoter hypermethylation was indeed observed in a fraction of tumor samples that nevertheless produced the overlapping transcripts." (PMID 34462486, 2021). "We explored the molecular mechanism underlying PTPRO effects by overexpression and knockdown of PTPRO in THP-1–derived and U937-derived macrophages, respectively, and following further treatment with or without tumor conditioned medium (CM)." (PMID 32581055, 2020). "The increased serum IL-6 activated STAT3/c-MYC signaling in peripheral monocytes, enhanced the transcription of miR-25–3 p, suppressed PTPRO expression, promoted PD-L1 through both JAK2/STAT3/c-MYC and JAK2/STAT1 signaling, and promoted tumor growth by enhancing T-cell exhaustion." (PMID 32581055, 2020). "Moreover, expression of some PTP tumor suppressors, such as PTPRD, PTPRO, PTPN12, PTPN13 and DUSP1, is reduced due to epigenetic silencing." (PMID 29558404, 2018). "Analysis of matched plasma samples shows that methylated PTPRO can be utilized as a peripheral tumor biomarker for noninvasive diagnosis and disease monitoring." (PMID 24090193, 2013). "Taken together, PTPRO can downregulate JAK2/STAT3 phosphorylation, and inhibit oncogenic signals by suppressing expressions of Bcl-2 and Snail; these events may subsequently induce mitochondria-dependent apoptosis and suppress tumor metastasis." (PMID 38182570, 2024). "IHC experiments revealed a significant proportion of patients with lower PTPRO protein levels in tumor specimens compared with the adjacent non-tumor tissues, and the overall PTPRO staining scores were remarkably lower in the tumor than in the non-tumorous lung." (PMID 38182570, 2024). "Additionally, the exact cargos from tumor-derived exosomes were not well identified except for PTPRO in the current study, future efforts for assessing the exosomal transcripts and proteins which are responsible for malignant phenotype are warranted." (PMID 34650968, 2021). "PRMT5-catalyzed histone H3 arginine 8 (R8) and H4R3 symmetric dimethylation has been shown to repress expression of several tumor suppressor genes such as Suppressor of Tumorigenicity 7 (ST7), retinoblastoma (RB) family of tumor suppressors, and Protein Tyrosine Phosphatase Receptor-type O (PTPROt)." (PMID 30613353, 2018).
cancer (25 papers, 2007 to 2025). A tumor composed of atypical neoplastic, often pleomorphic cells that invade other tissues. "The downregulation of PTPRO in cancers results from its epigenetic silencing, caused by hypermethylation of the promoter region of the PTPRO encoding gene." (PMID 38999976, 2024). "PTPRO decrease has been linked to promoter hypermethylation in several cancer types." (PMID 38182570, 2024). "However, the frequency of PTPRO methylation detected in plasma was lower than in cancer tissues and less association of methylation were found in plasma with clnicopathological data." (PMID 24919593, 2014). "Both Src and JAK2 are tyrosine kinases, and JAK2 not only plays an important role in cancer cell apoptosis and metastasis but is activated by PTPRO deletion." (PMID 40016288, 2025). "JAK2/STAT3 signaling has been widely implicated in mitochondria-dependent apoptosis and cancer metastasis, thus attracted our attentions and western blotting was applied to compare JAK2/STAT3 pathway activity in PTPRO-overexpressing and control groups." (PMID 38182570, 2024). "We and others have found that in many cancer types PTPRO downregulation can be partially attributed to promoter methylation." (PMID 37485875, 2023). "Protein tyrosine phosphatase receptor type O (PTPRO) regulates multiple kinases and pathways and has been implied to play a regulatory role in immune cell infiltration in various cancers." (PMID 36003382, 2022). "Based on the fact that PTPRO can sensitize cancer cells to different therapies, we overexpressed PTPRO in ERBB2-positive cancer cells and demonstrated that the overexpressed PTPRO is capable of reversing lapatinib-insensitivity." (PMID 35431974, 2022). "We analyzed the data on the levels of PTPRO mRNA to compare the expression of PTPRO in various forms of cancers." (PMID 35003364, 2021). "Nevertheless, to our knowledge no studies have systematically investigated the expression and prognostic value of PTPRO in various human cancers." (PMID 35003364, 2021). "In this manuscript, we systematically investigated the differential expression of PTPRO as well as its prognosis values in different human cancers." (PMID 35003364, 2021). "Herein, we performed bioinformatic analyses and revealed the potential oncogenic role of PTPRO in specific cancer types." (PMID 35003364, 2021). "Herein, we employed the PrognoScan 19 and Oncomine 20 databases, as well as Kaplan-Meier plotter 21 to conduct a comprehensive analysis of PTPRO expression and its link with cancer prognosis." (PMID 35003364, 2021). "Although we have identified the altered effect of miR-6803-5p on cancer inflammation is dependent on NF-κB, more studies are warranted to elucidate the downstream signaling pathway of miR-6803-5p/PTPRO involved in colorectal carcinogenesis." (PMID 31827380, 2019). "miR-6803-5p can promote cancer cell proliferation and invasion and enhance inflammation through PTPRO/NF-κB axis in CRC, which serves as a useful target for CRC." (PMID 31827380, 2019). "Epigenetic inactivation of the protein tyrosine phosphatase receptor-type O gene (PTPRO) has been described in several types of cancer." (PMID 24919593, 2014). "PTPRO may exert its anticancer effect by regulating multiple signalling pathways in a cancer type-specific manner." (PMID 40016288, 2025). "Protein tyrosine phosphatases such as PTPRO are important in cancer progression." (PMID 40016288, 2025). "Since PTPRO expression is inversely correlated with cancer cell metastasis, increasing PTPRO expression could be a potential therapeutic strategy to prevent BC metastasis." (PMID 40016288, 2025). "Furthermore, hypermethylation of the PTPRO gene has been proposed as a potential biomarker for early cancer detection." (PMID 39065585, 2024).
cancer (continued). "Given that hippocampal PTPRO expression is tightly associated with neurocognitive-related functions and decreases with age, we hypothesized that the age-related decrease in hippocampal PTPRO might be a mechanistic factor for CRCI in elderly cancer patients." (PMID 37485875, 2023). "We first analyzed the expression levels of PTPRO in pan-cancer tissues via the TIMER database." (PMID 36816740, 2023). "Therefore, the suppressive role of PTPRO in cancer is due to STAT3 inactivation, which instead appears upregulated when PTPRO levels are reduced." (PMID 37508414, 2023). "In particular, the Jak-STAT signaling pathway controlling cellular processes including proliferation, differentiation and apoptosis 27, 28, which may explain the anti-cancer activity of PTPRO inhibitor." (PMID 35003364, 2021). "We conducted several analyses to determine whether there is a link between cancer prognosis and the expression of PTPRO." (PMID 35003364, 2021). "The results above revealed that PTPRO expression affects the prognosis of specific types of cancer." (PMID 35003364, 2021). "Therefore, the specific objective here was to better characterize the potential functions of PTPRO in human cancers." (PMID 35003364, 2021). "We further assessed the expression of PTPRO expression in human cancers." (PMID 35003364, 2021). "Currently, the roles of PTPRO in human cancers remain elusive." (PMID 35003364, 2021). "Therefore, PTPRO/PTPROt confers a promising therapeutic target in inflammation and cancers and other relevant diseases." (PMID 34880876, 2021). "Several recent studies have elucidated certain miRNAs are associated with PTPRO in kinds of diseases but not cancer, for instance, miR-17-92 and miR-548Cc-5p." (PMID 31827380, 2019). "Notably, both our studies and that of others have indicated that protein tyrosine phosphatase receptor type O (PTPRO) may serve as a therapeutic target across various cancers." (PMID 39065585, 2024). "In addition to alleviating the CRCI phenotypes, BBR might modify the trajectory of CRCI at least in a subgroup of elderly cancer patients with preexisting PTPRO downregulation." (PMID 37485875, 2023). "In addition, PTPRO knockdown robustly reduced the sensitivity of the cancer cells to lapatinib." (PMID 35431974, 2022). "Protein tyrosine phosphatase receptor type O (PTPRO) suppresses tumors tumorigenesis and progression in several cancers." (PMID 36969840, 2023). "PTPRO-based PTS provides a new immune cell paradigm for prognosis, which is valuable for immunotherapy decisions in cancer patients." (PMID 36003382, 2022). "Furthermore, we also determined that higher CD300LG levels, but not PTPRO, IL6ST or CD48, were associated with better overall survival in cancer patients." (PMID 38386350, 2024). "However, these previous studies did not address the mechanism that results in the decreased PTPRO in cancer cells or immune cells." (PMID 32581055, 2020).
genetic disease (2 papers, 2017 to 2018). "These approaches allowed to establish genetic diagnoses in 24% of the patients screened, widened the spectrum of genetic disease entities presenting with SRNS phenotype (COL4A3-5, CLCN5), and contributed to the discovery of new disease causing genes (MYOE1, PTPRO)." (PMID 30065916, 2018).
brain diseases (1 paper, 2024). "Therefore, both PTPRO and GADD45A may play significant roles in the pathogenesis of brain diseases." (PMID 38212777, 2024).
immune disorders (1 paper, 2021). "As demonstrated by luciferase reporter assay, the well-established target of miR-6869-5p is PTPRO, a key factor in regulating macrophage mediated inflammation and immune disorders." (PMID 34007244, 2021).
PTPRO also shares sentences with these, for which no sentence is quoted: breast (3 papers); colorectal tumor (2); glomerulopathies (2); steatosis (2); acute myeloid leukemia (1); adenocarcinoma (1); Alport syndrome (1); Anxiety (1); asthma (1); bladder cancer (1); blood cancer (1); cholangiocarcinoma (1); diffuse large B-cell lymphoma (1); esophageal squamous cell carcinoma (1); focal segmental glomerulosclerosis (1); Fulminant hepatitis (1); IgA nephropathy (1); Insulin resistance (1); invasive breast carcinoma (1); kidney (1); kidney disease (1); lupus nephritis (1); Macrocephaly (1); melanoma (1); multiple myeloma (1); pancreatic adenocarcinoma (1); prostate adenocarcinoma (1); rectum adenocarcinoma (1); renal failure (1); renal fibrosis (1).
A further 7 diseases each share a sentence with PTPRO in 1 paper.